TMPRSS2 (transmembrane serine protease 2)
Diseases named in the same sentence as TMPRSS2 in open-access papers (continued):
Sharing a sentence is not in itself a finding about the gene and the disease.
periodontitis (4 papers, 2022 to 2023). An acute or chronic inflammatory process that affects the tissues that surround and support the teeth. "Other than ACE2, BMAL1, CD147, FURIN, and TMPRSS2, more genes, including CD26(DPP4), IFITM3, HLA, ABO, SLC6A20, GSTT1-M1, and DBP, have also been implicated in SARS-CoV-2 and periodontitis." (PMID 36366382, 2022). "ACE2, TMPRSS2, FURIN, and CD147, which are SARS-CoV-2 primary receptors and co-receptors, are overexpressed in the periodontal tissues of periodontitis patients, presenting with inflammation, periodontal pathogens, and damage-induced pyroptosis." (PMID 36366382, 2022). "Therefore ACE2, TMPRSS2, FURIN, CD147, and BMAL1 are the crossroads between SARS-CoV-2 and Periodontitis genes." (PMID 36366382, 2022).
thyroid cancer (4 papers, 2020 to 2023). "A few in silico studies pointed to a downregulated expression of TMPRSS2 in thyroid carcinoma compared to healthy thyroid tissues; we were not able to observe this, since according to our data, TMPRSS2 did not seem to play a role in thyroid tumorigenesis." (PMID 37568724, 2023). "In thyroid carcinomas, TMPRSS2 cytoplasmic expression was decreased in the absence of CLT (p = 0.031), which was also observed, but restricted to the PTC histotype." (PMID 37568724, 2023). "The AUC > 0.80 shown by TMPRSS2, CLEC4M and DPP4 suggests that these genes may act as effective molecular markers for kidney, liver and thyroid cancers." (PMID 32970391, 2020).
acute kidney injury (3 papers, 2020 to 2023). Sudden and sustained deterioration of the kidney function characterized by decreased glomerular filtration rate, increased serum creatinine or oliguria. "The expression of apparatus mediating SARS-CoV-2 entry, including angiotensin-converting enzyme 2, transmembrane protease serine 2 (TMPRSS2) and a disintegrin and metalloprotease 17 (ADAM17), within the renal tubular cells is highly associated with acute kidney injury mediated by SARS-CoV-2." (PMID 33153216, 2020).
acute pancreatitis (3 papers, 2020 to 2023). An acute inflammatory process that leads to necrosis of the pancreatic parenchyma. "This membrane fusion has been reported to be prevented by the TMPRSS2 inhibitor nafamostat, which is a drug for acute pancreatitis." (PMID 35215982, 2022). "The same analysis was performed for camostat, which is also a drug for acute pancreatitis and a known TMPRSS2 inhibitor." (PMID 35215982, 2022). "Parenthetically, the expression of TMPRSS2 in acinar cells underscores the rationale for using a TMPRSS2 inhibitor (camostat mesylate) in acute pancreatitis." (PMID 32545271, 2020).
Alzheimer disease (3 papers, 2023 to 2025). A progressive, neurodegenerative disease characterized by loss of function and death of nerve cells in several areas of the brain leading to loss of cognitive function such as memory and language. "The comparisons of postmortem aged brain specimens revealed reduced ACE2, TMPRSS2, but elevated STAT2 protein levels in individuals with DS and Alzheimer’s disease (DS-AD) compared to control and Alzheimer’s disease (AD) group." (PMID 40445428, 2025). "Although this allosteric in silico study by our group was focused on Alzheimer’s disease, the scope can be expanded to include drug candidates targeting multiple SARS-CoV-2 receptors, such as RNA polymerase, main protease, spike protein, ACE2 receptor, and transmembrane protease serine 2 (TMPRSS2)." (PMID 37958503, 2023).
breast tumor (3 papers, 2022 to 2025). "However, promoter analysis of TMPRSS2 and SYK using SMART App showed methylation of these promoters in breast tumor patient samples." (PMID 36474139, 2022).
encephalitis (3 papers, 2021 to 2025). An acute inflammatory process affecting the brain parenchyma. "This study assesses the cerebrospinal fluid (CSF) levels of the viral receptor angiotensin-converting enzyme 2 (ACE2) and of the serine protease TMPRSS2 fragments in patients with SARS-CoV-2 infection presenting encephalitis (CoV-Enceph)." (PMID 40036349, 2025). "We also analyzed whether levels of the ACE2 and TMPRSS2 species are differentially affected in patients with encephalitis unrelated to SARS-CoV-2 infection (Enceph)." (PMID 40036349, 2025). "Here, we aimed to determine the levels of ACE2 and TMPRSS2 in the CSF of patients with mild SARS-CoV-2 infection without major neurological symptoms (CoV) and patients severely affected with encephalitis (CoV-Enceph)." (PMID 40036349, 2025). "sACE2 was detected in the cerebrospinal fluid of COVID-19 patients with encephalitis, while those without encephalitis showed normal levels of ACE2 and TMPRSS2." (PMID 41303587, 2025). "The CoV patients without encephalitis displayed unaltered CSF levels of ACE2 and TMPRSS2 species." (PMID 40036349, 2025).
Granuloma (3 papers, 2020 to 2023). A compact, organized collection of mature mononuclear phagocytes, which may be but is not necessarily accompanied by accessory features such as necrosis. "A reverse correlation between IL6 and ACE2, NRP1 and TMPRSS2 gene expression in periapical abscesses and granuloma was noted." (PMID 35163355, 2022). "Next, using a previously unpublished scRNA-seq dataset consisting of granuloma and adjacent, uninvolved lung samples from Mtb-infected NHPs (Macaca fascicularis) collected with Seq-Well S3, we identified subsets of epithelial cells expressing ACE2 and TMPRSS2 (STAR Methods)." (PMID 32413319, 2020).
Hepatic steatosis (3 papers, 2022 to 2024). Steatosis is a term used to denote lipid accumulation within hepatocytes. "We analysed ACE2 and TMPRSS2 expression and localisation in nine cases of fatty liver disease and five controls by immunohistochemistry." (PMID 38074511, 2024). "Finally, we showed that in the liver of patients with NAFLD, the SARS-Cov-2 entry factors ACE2 and TMPRSS2 are inversely correlated with the amount of hepatic steatosis and with the degree of necro-inflammation." (PMID 36366497, 2022). "Taken together, our experimental and meta-analyses data showed low general levels of ACE2 and TMPRSS2 in all liver cell subsets tested, with upregulation of ACE2 mRNA31,32 and protein in fatty liver disease." (PMID 38074511, 2024). "In fatty liver disease, the mRNA expression of ACE2 and that of the SARS-CoV-2 co-receptor TMPRSS2 are upregulated." (PMID 38074511, 2024).
kidney chromophobe (3 papers, 2022 to 2023). "Assessment of protein expression of ACE2, TMPRSS2 and NRP1 in clear cell, papillary and chromophobe renal cell carcinoma." (PMID 36595529, 2023).
male infertility (3 papers, 2015 to 2021). The inability of the male to effect fertilization of an ovum after a specified period of unprotected intercourse. "Using bioinformatics analysis, we speculate that the predicted miRNAs including miR-125a-5p, miR-125b-5p, miR-574-5p, and miR-936 as regulators of ACE2 and miR-204-5p as a modulator of TMPRSS2 are associated with male infertility." (PMID 34204705, 2021).
metastatic carcinoma (3 papers, 2017 to 2021). A carcinoma which has spread from the original site of growth to another anatomic site. "The highest fusion rate was the TMPRSS2-ERG fusion in PRAD, with 21.63% in primary cancer and 22.34% in metastatic cancer." (PMID 29038591, 2017).
thyroid (3 papers, 2022 to 2023). "No statistical differences were found in TMPRSS2 protein expression among the different histotypes and subtypes of the thyroid lesions, for both cytoplasmic and nuclear expression." (PMID 37568724, 2023).
acinar adenocarcinoma (2 papers, 2018 to 2025). "MAP3K7 deletions are associated well with the TMPRSS2-ERG absence, which is more common in ductal than acinar adenocarcinomas." (PMID 29581876, 2018). "Radical prostatectomy on November 1, 2024 revealed a small residual acinar adenocarcinoma focus with perineural invasion, negative surgical margins, and molecular evidence of TMPRSS2::ERG gene fusion and PTEN loss." (PMID 41267989, 2025). "TMPRSS2-ERG fusion occurs in 11% of the ductal component and in 5% of the acinar component of a mixed tumor, compared with 45%–50% of pure acinar adenocarcinomas." (PMID 29581876, 2018).
allergic disease (2 papers, 2024). An immune response that occurs following re-exposure to an innocuous antigen, and that requires the presence of existing antibodies against that antigen. "The nasal expression of ACE2 and TMPRSS2 depends on age, allergic disease, and medication." (PMID 39597953, 2024). "TMPRSS2 reduces the recognition of viruses through human defense mechanisms; however, type 2 inflammation, in which interleukin (IL)-4, IL-5, and IL-3 are important inflammatory factors, acts as the inflammatory basis of allergic diseases in children." (PMID 38646512, 2024).
bone tumor (2 papers, 2017 to 2019). "Furthermore transcriptional regulation by TMPRSS2-ERG in bone tumor growth reveals the reliance of bone tumor growth on intra-tumoral androgen synthesis." (PMID 31638934, 2019). "We utilized ERG knockdown approach in TMPRSS2-ERG positive cells and targeting the AR function with enzalutamide for bone tumor growth." (PMID 31638934, 2019).
colitis (2 papers, 2025). Inflammation of the colon. "Activation of matriptase, a proposed substrate of TMPRSS2, protected mice from dextran sodium sulfate-induced experimental colitis and promoted intestinal barrier function." (PMID 40227199, 2025). "This is striking, given findings that non-genotyped patients with IBD (± inflammation) showed no change in ACE2 or TMPRSS2 expression, whereas experimental colitis in mice reduced gut epithelial Ace2 expression." (PMID 39756517, 2025).
Crohn disease (2 papers, 2020 to 2021). A gastrointestinal disorder characterized by chronic inflammation involving all layers of the intestinal wall, noncaseating granulomas affecting the intestinal wall and regional lymph nodes, and transmural fibrosis. "Using single-cell data from the ileum (distal small bowel) in Crohn disease patients, we found that ACE2 and TMPRSS2 had low to undetectable expression in the non-epithelial cells." (PMID 33156843, 2020).
Disseminated intravascular coagulation (2 papers, 2020 to 2023). Disseminated intravascular coagulation is characterized by the widespread activation of coagulation, which results in the intravascular formation of fibrin and ultimately thrombotic occlusion of small and midsize vessels. "We have previously reported that nafamostat mesylate, an existing Japanese drug used for acute pancreatitis and disseminated intravascular coagulation (DIC), effectively inhibits MERS-CoV S protein-mediated membrane fusion by targeting TMPRSS2 priming activity." (PMID 32532094, 2020).
HIV-1 infection (2 papers, 2021). The type species of lentivirus and the etiologic agent of acquired immunodeficiency syndrome (AIDS). "Next, we evaluated if ACE2 and/or TMPRSS2 levels are affected by HIV-1 infection." (PMID 34325716, 2021). "We then investigated if HIV-1 infection could lead to alterations of ACE2 or TMPRSS2 expression in pericytes." (PMID 34325716, 2021). "In addition, a significant increase in the TMPRSS2 protein level was observed post HIV-1 infection." (PMID 34325716, 2021). "Taking into consideration possible interactions between SARS-CoV-2 and HIV-1, we also evaluated the expression of ACE2 and TMPRSS2, i.e., the main SARS-CoV-2 receptors, in these cells after HIV-1 infection." (PMID 34325716, 2021). "Additionally, HIV-1 infection upregulated ACE2 and TMPRSS2 expression in astrocytes and microglial cells." (PMID 34325716, 2021). "Additionally, HIV-1 infection of brain astrocytes and microglia cells upregulated ACE2 and TMPRSS2 expression levels." (PMID 34325716, 2021). "Additionally, HIV-1 infection upregulated ACE2 and TMPRSS2 expression in brain astrocytes and microglia cells." (PMID 33655239, 2021). "Therefore, we proposed to evaluate whether HIV-1 infection modulates the expression levels of ACE2 and TMPRSS2." (PMID 34325716, 2021).
infertile (2 papers, 2021 to 2023). "In this study, the expression profiles of miRNAs and lncRNAs which regulate ACE2 “the hottest targets of SARS-CoV-2” and TMPRSS2 “S protein priming” were analyzed comprehensively in infertile men by bioinformatics approaches." (PMID 34204705, 2021). "Furthermore, they demonstrated a higher expression of ACE2 and TMPRSS2 in the testes of infertile men than normal." (PMID 34204705, 2021).
Lewis lung carcinoma (2 papers, 2022 to 2025). "RG4 stabilizers were capable to reduce endogenous TMPRSS2 expression in murine Lewis lung carcinoma cells (LLC)." (PMID 35301316, 2022).
muscle ache (2 papers, 2022). "Both were linked strongly to fever, headache, and dysponea, whilst the ACE2 SNP was strongly linked to sore throat and muscle ache, and the TMPRSS2 SNP to diarrhea." (PMID 35996506, 2022).
myocarditis (2 papers, 2012 to 2021). Myocarditis is a condition that is characterized by inflammation of the heart muscle (myocardium). "After gaining entry through ACE2 aided by TMPRSS2, the SARS-CoV-2 causes serious complications of the cardiovascular system leading to myocarditis and other myocardial injuries apart from causing lung, kidney and brain dysfunctions." (PMID 33981235, 2021).
pulmonary edema (2 papers, 2022 to 2023). Accumulation of fluid in the lung tissues causing disturbance of the gas exchange that may lead to respiratory failure. "It remains to be seen whether a functional relevance of TMPRSS2-dependent ENaC activation becomes evident in challenging conditions where increased alveolar or renal ENaC activity is needed, for example, in pulmonary edema or salt deprivation, respectively." (PMID 35504352, 2022).
radicular cysts (2 papers, 2021 to 2023). "Furthermore, 1-nonadecene significantly upregulated the gene expression of ACE-2, NRP-1, and TMPRSS2, indicating a possible higher viral load in radicular cysts compared to other periapical lesions but less than the healthy control." (PMID 34749700, 2021).
renal cell carcinoma (2 papers, 2023 to 2025). "We also disrupted the same three genes in the renal cell carcinoma line SW156, which expresses moderate levels of ACE2 and LGMN, but low to almost undetectable levels of TMPRSS2 and serves as a model for SARS-CoV-2 infection of the kidney." (PMID 40674406, 2025).
Respiratory distress (2 papers, 2020 to 2021). Respiratory distress is objectively observable as the physical or emotional consequences from the experience of dyspnea. "ACE2 and TMPRSS2 levels positively correlated with age, which was also strongly associated with respiratory distress." (PMID 33958627, 2021).
steatosis (2 papers, 2022 to 2024). Increased lipid within the cytoplasm of cells. "Interestingly, we found that hepatic ACE2 and TMPRSS2 were inversely correlated with the amount of steatosis and were statistically significantly lower in patients with a higher NAS score." (PMID 36366497, 2022). "The expression of TMPRSS2 remained unchanged in MASLD, whereas the MERS-CoV receptor dipeptidyl peptidase 4 (DPP4) and the SARS-CoV-2 coreceptor CLEC4M were lower in steatosis and steatohepatitis, with respect to controls." (PMID 38074511, 2024).
acquired immunodeficiency (1 paper, 2021). "When the relative expression of ACE2 and TMPRSS2 increased, the infiltrating degree of all these cells tended to decrease, suggesting that the expression of these two proteins was related to the congenital and acquired immunodeficiency." (PMID 34412632, 2021).
acute lymphoblastic leukemia (1 paper, 2025). Leukemia with an acute onset, characterized by the presence of lymphoblasts in the bone marrow and the peripheral blood. "We selected the T-cell acute lymphoblastic leukemia cell line Loucy as it expresses moderate levels of endogenous KCNA6 and LGMN, low levels of TMPRSS2, and low to undetectable levels of ACE2." (PMID 40674406, 2025).
adenoma (1 paper, 2021). A neoplasm arising from the epithelium. "Finally, by performing an in silico analysis, we describe the mRNA expression of ACE2, TMPRSS2 and the genes encoding their co-receptors CTSB, CTSL and FURIN in normal adrenal and adrenocortical tumors (both adenomas and carcinomas)." (PMID 34594302, 2021).
age (1 paper, 2021). A temporal measurement of the time period elapsed since an identifiable point in the life cycle of an organism. "In turn, the edges may correspond to countervailing connectors and pathways: TMPRSS2 promoting the contribution of testosterone excess and ACE-2 promoting the role of age-related testosterone deficiency." (PMID 33796068, 2021).
allergic asthma (1 paper, 2024). A asthma with a basis in a pathological type I hypersensitivity reaction. "Consequently, it is debated if patients with allergic asthma who express higher levels of TMPRSS2 are more susceptible to SARS-CoV-2 infection." (PMID 38541703, 2024).
Anxiety (1 paper, 2023). Intense feelings of nervousness, tension, or panic often arise in response to interpersonal stresses. "We were interested to know whether a variable degree of anxiety/stress during Covid-19 pandemic might increase the expression pattern of ACE2 and TMPRSS2 comparing to those in endometria collected before pandemic." (PMID 37142998, 2023).
autosomal recessive nonsyndromic deafness- (1 paper, 2020). "In addition, TMPRSS2, -5, and -10 were found to be expressed in inner ear tissues and were mapped within the HL loci PKSR7 (Pakistani family), autosomal recessive nonsyndromic deafness-24 (DFNB24), and autosomal recessive nonsyndromic deafness-25 (DFNB25), respectively." (PMID 32235586, 2020).
bronchiolitis (1 paper, 2023). Inflammation of the bronchioles characterized by swelling of the bronchioles and mucus accumulation. "Bronchi and bronchioles affected by necrotizing bronchitis and bronchiolitis had diminished TMPRSS2 transcripts with fewer cells containing TMPRSS2 transcripts." (PMID 38883409, 2023).
carcinosarcoma (1 paper, 2025). A malignant tumor composed of a mixture of carcinomatous and sarcomatous elements. "Genomic analysis revealed a TMPRSS2-ERG fusion, confirming a common clonal origin and transdifferentiation from adenocarcinoma to carcinosarcoma." (PMID 40969255, 2025).
endometriosis (1 paper, 2024). The growth of functional endometrial tissue in anatomic sites outside the uterine body. "In women with endometriosis, ACE2 and TMPRSS2 expression is significantly downregulated compared to healthy controls." (PMID 39331336, 2024).
eye infection (1 paper, 2021). An infectious process affecting any part of the eye. "Using EyeDiseases, we investigated SARS-CoV-2 potential tropism in eye infection and found that the SARS-CoV-2 entry factors, ACE2 and TMPRSS2 are highly correlated with cornea and keratoconus, suggest that ocular surface cells are susceptible to infection by SARS-CoV-2." (PMID 34085038, 2021).
Graves disease (1 paper, 2022). Graves' disease is an autoimmune disorder that leads to overactivity of the thyroid gland (hyperthyroidism).It is caused by an abnormal immune system response that causes the thyroid gland to produce too much thyroid hormones. "TMPRSS2 was stained in the colloid of the normal thyroid, Graves’ disease, and Hashimoto’s thyroiditis, and was more strongly expressed than in rats." (PMID 35625425, 2022). "We also analyzed the expression patterns of ACE2 and TMPRSS2 in 9 Sprague-Dawley rats and 15 human thyroid tissues, including 5 normal, 5 with Hashimoto’s thyroiditis, and 5 with Graves’ disease, by immunohistochemistry (IHC) and immunofluorescence." (PMID 35625425, 2022).
HCMV infection (1 paper, 2023). "Following HCMV infection we observed a striking upregulation of ACE2 protein, with a small increase in TMPRSS2, in both immunofluorescence and immunoblot assays." (PMID 36408607, 2023). "However, HCMV infection clearly led to upregulation of ACE2 and substantial upregulation of TMPRSS2 when analyzed by both indirect immunofluorescence and western blot." (PMID 36408607, 2023).